KRAS (KRas proto-oncogene, GTPase)
Diseases named in the same sentence as KRAS in open-access papers (continued):
Sharing a sentence is not in itself a finding about the gene and the disease.
colorectal cancer (continued). "Among the three human RAS oncogenes (KRAS, NRAS and HRAS), KRAS is the most frequently mutated isoforms in pancreas, lung, and colorectal cancer." (PMID 33691728, 2021). "The protein kinases RAF and SRC are validated therapeutic targets in KRAS-mutant pancreatic ductal adenocarcinomas, colorectal cancers and non-small-cell lung cancers and we show that both must be inhibited to block growth of these cancers." (PMID 33130216, 2021). "We reported a novel small RNA sequence, MIRTX, that significantly inhibits KRAS-mutant colorectal cancer cell growth in vitro and in vivo by suppressing NF-kB signaling pathways via direct inhibition of CXCR2 and PIK3R1." (PMID 34834512, 2021). "KRAS, a monomeric membrane-localized GTPases, is the most frequently mutated RAS isoform in various cancers, such as pancreatic adenocarcinoma (90%), colorectal cancer (45%) and lung adenocarcinoma (35%), and has been found to play pivotal role in oncogenesis." (PMID 34345014, 2021). "Determining the status of EGFR and KRAS mutations is crucial for guiding treatment in NSCLC patients receiving EGFR tyrosine kinase inhibitors and colorectal cancer patients treated with anti-EGFR therapy respectively." (PMID 34803167, 2021). "KRAS is common in pancreatic adenocarcinomas and colorectal cancer, NRAS in melanoma, thyroid cancer, and leukemia." (PMID 34604242, 2021). "The combination of curcumin and regorafenib only showed additive/synergistic effects in KRAS-mutant and not KRAS-wildtype cells, suggesting their possible use in the treatment KRAS-mutant colorectal cancer." (PMID 34867402, 2021). "In colorectal cancer, KRAS activation is known to induce CXCL3 expression and the induction of MDSCs with CXCR2, the receptor of CXCL3." (PMID 34359568, 2021). "In colorectal cancer, the most observed pathway changes are IGF2 overexpression and KRAS mutation which are located upstream in the PI3K/AKT pathway and activates them." (PMID 34572902, 2021). "Here, we report that the majority of the KRAS mutant colorectal cancer (CRC) cells upregulate selected AATs (SLC7A5/LAT1, SLC38A2/SNAT2, and SLC1A5/ASCT2), which correlates with enhanced uptake of AAs such as glutamine and leucine." (PMID 34003553, 2021). "In colorectal cancer (CRC), cetuximab use is guided by the presence of RAS mutations, with KRAS alterations being a robust predictor of both adverse prognosis and cetuximab resistance." (PMID 34546978, 2021). "This is the first randomized phase II, open-label, multicenter study to compare the efficacy and safety of SOX+bevacizumab with SOX+cetuximab in patients with previously untreated recurrent advanced colorectal cancer with wild-type KRAS." (PMID 34425776, 2021). "It was also shown that EMICORON in combination with chemotherapy improved anti-tumor efficacy as well as decreased both mRNA and protein expression levels of KRAS in colorectal cancer PDXs." (PMID 33801965, 2021). "Numerous studies have reported that KRAS and NRAS mutations occur respectively in 45% and 5–8% of worldwide colorectal cancer patients." (PMID 33784337, 2021). "This review aims to highlight the recent findings that have improved our understanding of KRAS and BRAF mutations in colorectal cancer and to describe new targeted therapies, used alone or in combination." (PMID 34063682, 2021). "The SNAI2 gene encoding SNAIL, a transcription factor and regulator of EMT, has been identified as a KRAS synthetic lethal target in colorectal cancer cell lines." (PMID 33777798, 2021). "In colorectal cancer, aberrant signals from cancer-associated pathways, such as WNT and activated KRAS, activate Hippo to promote tumor growth and metastasis." (PMID 34577783, 2021). "The mRNA-5671 (Moderna) targets KRAS and is being currently evaluated in patients with KRAS-mutant advanced or metastatic non-small cell lung cancer, colorectal cancer, or pancreatic adenocarcinoma (ClinicalTrials.gov, 2020e)." (PMID 33816449, 2021).
colorectal cancer (continued). "The analysis focused not only on tumor location, mucin phenotype, and PD-L1 status but also on factors such as KRAS and BRAF mutations, which are important in colorectal cancer." (PMID 34797780, 2021). "By contrast, in a study on colorectal cancer, cases with KRAS mutations demonstrated a different role of this oncogene in the malignant phenotype, suggesting a role of KRAS in the metabolic adaptation mechanism to nutritional stress in colorectal cancer." (PMID 34680237, 2021). "Rigosertib (RGS) exhibited a cytotoxic effect against colorectal cancer cells, which was greater in KRAS-mutant cells." (PMID 34347396, 2021). "One notable example of the progress in VitC pre-clinical research is the recent work in hard-to-treat Kirsten Rat Sarcoma Viral Oncogene Homolog (KRAS) driven tumours, such as KRAS mutant colorectal cancer (CRC)." (PMID 34717701, 2021). "Poloppin, a recently developed PBD inhibitor, was shown to effectively target KRAS-expressing colorectal cancer xenografts." (PMID 35156101, 2021). "The successful isolation of specific scFv binders to mKRAS G12V antigen is analogous to a guidance system that is able to carry a very lethal toxin load, thus enabling the selective killing of KRAS-positive colorectal cancer cells while sparing normal cells." (PMID 33959410, 2021). "For example, anti-EGFR therapy is excluded in patients with KRAS mutant colorectal cancer due to receptor tyrosine kinase (RTK)-independent activation of mutant KRAS." (PMID 34680229, 2021). "BRAF is a downstream effector of KRAS, and its prognostic value in colorectal cancer is widely accepted." (PMID 34884530, 2021). "The lower response rate in colorectal cancer patients (7.1%) suggests a different KRAS dependency across diverse tumor types harboring the same mutation." (PMID 33777798, 2021). "The YAP1/SIX2 axis is responsible for DDX3X-induced cell invasiveness in colorectal cancer harbouring wild-type KRAS." (PMID 33627125, 2021). "KRAS mutant colorectal cancers have shown to be sensitive to a more recent G4 ligand known as EMICORON." (PMID 33801965, 2021). "Together, these findings imply the oncogenic property of ACSL4 in colon cancers, with 30–40% of the tumors carrying a KRAS mutation, in which KRAS G12V mutation is one of the major pathologic features of SW480 as a colorectal cancer cell line." (PMID 33466836, 2021). "Colorectal cancer patients need to undergo KRAS, NRAS, BRAF, HER2 and microsatellite instability analysis." (PMID 34681592, 2021). "A retrospective study reported a significantly higher 18F-fluorodeoxyglucose accumulation detected with positron emission tomography in KRAS mutant colorectal cancer patients compared with wild-type ones." (PMID 33777798, 2021). "The use of a colorectal cancer cell line, on the other hand, was precluded since oncogenic KRAS has repeatedly been shown to significantly downregulate the expression of PTEN." (PMID 34943931, 2021). "Recently, CD239 was found to play a functional role in the metastatic spreading of monoallelic KRAS-mutant driven colorectal cancer by mediating interactions between the tumor and its microenvironment." (PMID 34611477, 2021). "In colorectal cancers (CRC), somatic mutations in KRAS, BRAF, or ERBB receptors occur in ~ 60 % of patient tumors." (PMID 34233735, 2021).
colorectal cancer (continued). "Examples of genes with a tissue-specific pattern of alteration include von Hippel Lindau tumor suppressor (VHL) in renal cancer, adenomatous polyposis coli (APC) in colorectal cancer, and KRAS in pancreatic, lung and colorectal cancers." (PMID 34143767, 2021). "RMC-4630 is also being tested in combination with combimetinib, a MEK inhibitor, and a recent update has shown some preliminary evidence of anti-tumour activity in KRAS-mutant colorectal cancer with tumour reduction in 37.5% of patients (3/8)." (PMID 33466360, 2021). "Clinical utility in previously untreated NSCLC and in other cancer types such as colorectal cancer will likely require greater efficacy than that seen to-date with KRAS G12C inhibitor monotherapy." (PMID 34845311, 2021). "To confirm the correct identification of KRAS mutant and wild-type amplicon we used three colorectal cancer stem cell lines (CSC1 carrying mutated KRASG12V, CSC2 carrying WT KRAS and CSC3 carrying mutated KRASG12D)." (PMID 34811396, 2021). "The results obtained should be verified in a homozygous wild-type KRAS-expressing colorectal cancer cell line such as SW48 HD PAR-006 from Horizon Discovery." (PMID 34943931, 2021). "In brief, our research confirmed that RGS exhibited a dramatic and selective anti-tumor effect in KRAS-mutant colorectal cancer when compared with RAS wild-type CRC, and that this anti-tumor effect was associated with RGS-induced inhibition of RAS signaling." (PMID 34347396, 2021). "Further analysis of hallmark gene sets showed that these lncRNAs in CRC tumorigenesis were also associated with hallmarks of epithelial mesenchymal, G2M checkpoint, hypoxia, and KRAS signaling, which only KRAS was often mentioned in colorectal cancer." (PMID 34954693, 2021). "Recognizing the critical role of KRAS mutants in colorectal cancer, we highlight the connections of KRAS signaling pathways in coordinating these functions." (PMID 33691728, 2021). "This suggests that the issue of KRAS activation needs to be tackled before EGFR inhibitors will be fully effective in more colorectal cancer cases." (PMID 33801965, 2021). "KRAS mutant colorectal cancers show enhanced cancer stem cell pathways which accelerate tumorigenesis." (PMID 34108518, 2021). "Summary of studies comparing KRAS/All-RAS mutation status in cfDNA and tumor tissue samples from colorectal cancer patients." (PMID 33770081, 2021). "Oncogenic KRAS has been previously identified to act in a cell-intrinsic manner to modulate multiple biological functions of colorectal cancer (CRC)." (PMID 33833221, 2021). "KRAS mutations are present in 30–50% of colorectal cancers and the RASCAL study of 2721 colorectal cancers showed that the presence of KRAS mutation was significantly associated with poorer prognosis." (PMID 33652647, 2021). "Curcumin appeared to act like a MEK inhibitor and most likely targets other genes as well, producing a synthetic lethal effect in KRAS-mutant colorectal cancer cells (Wu CS." (PMID 34867402, 2021). "There is a growing unmet need for a personalized therapy approach for patients with KRAS-mutant colorectal cancer." (PMID 34944853, 2021).
colorectal cancer (continued). "Cetuximab is a recombinant mouse/human chimeric monoclonal antibody that targets EGFR to treat patients with EGFR- and wild-type Kirsten rat sarcoma 2 viral oncogene homolog (KRAS)-expressing colorectal cancer." (PMID 33802964, 2021). "For example, PCR-based ctDNA assays for EGFR genotyping in non-small cell lung cancer, and for KRAS genotyping in colorectal cancer have demonstrated clinical validity and thus have received regulatory approval in the United States and Europe." (PMID 34194620, 2021). "We summarize recent knowledge regarding the effects of KRAS and BRAF mutations in the setting of colorectal cancer and discuss the new therapies under development." (PMID 34063682, 2021). "A mTOR inhibitor, AZD8055 with a BCL-2 inhibitor exhibited synergistic cytotoxic effects in KRAS-mutant colorectal cancer cells." (PMID 34301278, 2021). "A recent study has shown that TNTs contribute to the progression of colorectal cancer by upregulating ERK (extracellular signal regulated kinase) expression in recipient cells by transferring mutant KRAS to these cells." (PMID 34921322, 2021). "Our recent article demonstrated the ability of targeting eIF4E (eukaryotic initiation factor 4E) phosphorylation to restore sensitivity to agents suppressing translation in KRAS mutant colorectal cancers." (PMID 33855169, 2021). "For instance, one study showed that Ago2 secretion within exosomes derived from isogenic colorectal cancer cells is regulated by KRAS activation and subsequent MEK-ERK signaling." (PMID 34203713, 2021). "In this manner, activation of KRAS induces MDSC-mediated resistance to antitumor immunity in patients with colorectal cancer." (PMID 34359568, 2021). "One of the most promising therapies for the treatment of KRAS mutant colorectal cancers is onvansertib, a selective adenosine triphosphate competitive inhibitor of serine/threonine polo-like-kinase 1 (PLK1)." (PMID 33801965, 2021). "A number of studies have shown that panitumumab combined with chemotherapy has good efficacy and safety in first-line, second-line, and third-line treatment of patients with wild type KRAS advanced colorectal cancer 87-89." (PMID 33391438, 2021). "It has previously been found that colorectal cancer cells with mutant KRAS are more sensitive to HT (exposure to 42 °C for 24 h) than cells with wild-type KRAS80." (PMID 34045581, 2021). "It has been shown that an increase in glucose uptake through enhanced GLUT1 expression is dependent on KRAS and BRAF mutation in colorectal cancer cell lines and sustained their survival." (PMID 33777798, 2021). "The KRAS, the most commonly mutated RAS oncogene occurs in about 45% of colorectal cancers with other rare RAS mutations representing an additional 15% of patients." (PMID 34132476, 2021). "KRAS mutations, BRAF mutations and SMAD4 mutations are less frequent in CSM2 colorectal cancers than in other subtypes." (PMID 34577783, 2021). "The use of synthetic alkylating agents recognizing and alkylating adenine residues of mutant KRAS have been developed and showed to inhibit the proliferation of KRAS mutant versus KRAS wild-type colorectal cancer cell lines." (PMID 33801965, 2021). "HGF, the main ligand of c-Met, induces cell migration and enhances the radiosensitivity of KRAS mutant colorectal cancer cells." (PMID 33391438, 2021). "Our study demonstrated the known driver mutations seen in colorectal cancer such as APC, KRAS, BRAF and PIK3CA, but also more novel mutations that would potentially be targetable by molecular agents." (PMID 33632293, 2021).
colorectal cancer (continued). "As KRAS and BRAF mutations are found in approximately 40% and 10% of human colorectal cancers (CRCs), respectively, the therapeutic use of vitamin C in treating patients with colorectal cancer presenting such type of mutations seems to be rational." (PMID 33652579, 2021). "Rab13 is proposed to mediate β1‐integrin exocytosis in KRAS‐dependent manner in colorectal cancer cells." (PMID 34401050, 2021). "Isolation of CTCs from colorectal cancer patients using the CellSearch system followed by their comprehensive genetic analysis with ACGH revealed mutations in known driver genes, such as KRAS, APC, and PIK3CA." (PMID 33448107, 2021). "Actionable variants of oncogenes, such as KRAS and PIK3CA, are frequently determined in both ERONs and colorectal cancers." (PMID 33557369, 2021). "In a retrospective study, we obtained KRAS and PIK3CA mutational status in a cohort of 153 patients with a first diagnosis of colorectal cancer receiving tumor surgery with curative intent." (PMID 34638442, 2021). "Upregulation of IL-10 transcription through MEK/ERK/AP-1 pathway was shown in KRAS mutant colorectal cancer cells and its secretion was required for the conversion of CD4+ T cell to CD4+FoxP3+ Treg cells." (PMID 33777798, 2021). "In a single-center retrospective study, we obtained KRAS and PIK3CA mutational status in a cohort of 153 patients with a first diagnosis of colorectal cancer receiving tumor surgery with curative intent." (PMID 34638442, 2021). "It has been shown that one of the compensatory cellular mechanisms of KRAS-mutant colorectal cancer cells is the increased phosphorylation of RTKs upon Akt inhibition." (PMID 34946644, 2021). "In colorectal cancer harbouring wild-type KRAS, DDX3X-induced KRAS elevated the level of ROS, which was followed by increased HIF1-α expression." (PMID 33627125, 2021). "We found that patients with regular aspirin use after the diagnosis of colorectal cancer and combined wild-type PIK3CA and mutated-KRAS tumors showed a significant survival benefit." (PMID 34638442, 2021). "The clinical activity of inhibitors of KRAS G12C is evidently higher in lung versus colorectal cancers." (PMID 34681592, 2021). "A novel bioactive compound containing a benzothiophene nucleus, DPS2, has been reported to show a potent anti-tumor effect in several colorectal cancer and melanoma cell lines harboring B-Raf or KRAS alterations." (PMID 34946644, 2021). "It looks like a novel metastatic colorectal cancer marker whose expression level permits for the selection of patients with wild-type KRAS cancer who more possibly respond to anti-EGFR treatment." (PMID 34350290, 2021). "Profiling of KRAS-expressing intestinal epithelioid cells IEC-6 with the combination of state-of-the-art cell surface proteomics and CRISPR/Cas-9 screens identified ATP7A as a lethal synthetic partner in KRAS-mutant colorectal cancers." (PMID 34440056, 2021). "Specifically, ALKBH5 gene DNA methylation positively correlated with ALKBH5 mRNA expression in KRAS mutant lung, and colorectal cancer cell lines, based on the CLLE database." (PMID 34016959, 2021). "KRAS inhibitors have shown promising results in nonsmall cell lung cancer patients, while only a few colorectal cancer patients were responsive to therapy, suggesting tissue-specific applicability of KRAS inhibition." (PMID 33804240, 2021).